AR (androgen receptor)
Diseases named in the same sentence as AR in open-access papers (continued):
Sharing a sentence is not in itself a finding about the gene and the disease.
prostate carcinoma (continued). "To better understand p44's role in prostate cancer and in the prostate gland, we used a yeast two-hybrid assay with full-length p44 as the bait to screen for proteins involved in p44's regulation of AR-mediated transcription." (PMID 23755100, 2014). "In prostate cancer (PC), the androgen receptor (AR) is a key transcription factor at all disease stages, including the advanced stage of castrate-resistant prostate cancer (CRPC)." (PMID 24753418, 2014). "The bicalutamide mechanism of action is to inhibit the activity of the androgen receptor (AR) thereby suppressing the viability and proliferation of prostate cancer cells that depend on it." (PMID 25278011, 2014). "While there are reports that AR positivity promotes autophagy in prostate cancer, there are reports of AR positivity with lower levels of autophagy activity." (PMID 25140630, 2014). "It is worth noting that the TMPRSS2-ETS fusion genes, commonly detected in approx-imately 50% human prostate cancers, are positively regulated by AR." (PMID 24508459, 2014). "Our results provide a compelling rationale for targeting the functional interaction between CAMK2N1 and AR signaling in clinical development to treat castration-resistant prostate cancer." (PMID 25296973, 2014). "The androgen receptor antagonist, and anti-prostate cancer activities for the synthesized compounds was evaluated using Bicalutamide as a reference drug." (PMID 25421248, 2014). "Increasingly it is being realized that ligand independent activation of AR is regulated in CACNA1D overexpressing prostate cancer cells." (PMID 24739220, 2014). "We show for the first time that the bone microenvironment itself significantly increased the tumor growth capacity of the prostate cancer cells, altered AR function and rendered the prostate cancer castrate resistant." (PMID 25278011, 2014). "One-half of the AR cistrome overlaps with that of GR in LNCaP-1F5 prostate cancer cells, and ligand-occupied GR is able to modulate the AR pathway." (PMID 24459135, 2014). "In summary, we identify a biochemical and functional link between CAMK2N1 with reduced expression in advanced prostate cancer and androgen receptor signaling in prostate cancer." (PMID 25296973, 2014). "Here, we demonstrate that SPOP recognizes a Ser/Thr-rich degron in the hinge domain of androgen receptor (AR)and induces degradation of full-length AR and inhibition of AR-mediated gene transcription and prostate cancer cell growth." (PMID 24508459, 2014). "We examined the effect of shikonin on the expression of AR in the androgen-responsive human prostate cancer cell lines LNCaP and 22RV1." (PMID 24573652, 2014). "Mechanistic studies demonstrated that dosage-sensitive sex reversal, adrenal hypoplasia critical region, on chromosome X, gene 1 (DAX-1), a negative regulator of androgen receptor in prostate cancer, was inhibited by miR-181 overexpression." (PMID 25187843, 2014). "Drugs targeting androgen receptor activity promote development of a neuroendocrine prostate cancer phenotype and increases the prevalence of neuroendocrine cells, and as more drugs in this category reach the clinic the occurrence is expected to rise." (PMID 25629002, 2014). "This microRNA is able to reduce v-erb-b2 avian erythroblastic leukemia viral oncogene homolog 2 (ERBB2) expression, a known oncogene whose expression increases in advanced prostate cancer, and to impair AR signaling pathway." (PMID 25309903, 2014). "In view of the findings that adrenal and local androgen synthesis can drive AR in castration resistant prostate cancer this would even enhance the inhibitory effect of metformin on tumor progression." (PMID 24913494, 2014). "Intriguingly, SPOP mutations (function to stabilize AR) and TMPRSS2-ETS translocations are mutually exclusive in prostate cancer." (PMID 24508459, 2014).
prostate carcinoma (continued). "Secondly, genetic studies showed that androgen receptor(AR) alteration, which is important in the development of prostate cancer, is also present in breast cancer." (PMID 24884785, 2014). "Minoxidil has been shown to enhance the growth of PC-3 cells which express KATP channel but lack an endogenous AR in serum-free conditions, and some potassium channel blockers suppress the growth of prostate cancer cell lines." (PMID 24742982, 2014). "In prostate cancer, clinical data and results from in vitro experiments imply that the NF-κB system is capable of interfering with androgen receptor (AR) signaling." (PMID 24272675, 2014). "Previous reports showed that an activated Wnt/β-catenin pathway and AR expression in prostate cancer are correlated with metastasis and aggressiveness." (PMID 24397471, 2014). "In this study we have investigated the relationship between Usp12, PHLPP and PHLPPL tumour suppressors in the regulation of AR transcriptional activity in prostate cancer (PC)." (PMID 25216524, 2014). "Newly approved chemotherapeutic agents such as Abiraterone (an oral selective inhibitor of CYP17A), which blocks androgen biosynthesis both within and outside the prostate cancer cells), and enzalutamide (blocks AR signaling) have improved overall survival." (PMID 25062956, 2014). "In support of experimental studies, we used the publicly available human prostate cancer genome data listed in TCGA, to confirm a direct correlation between mRNA expression of AR and integrin α2 (Spearman’s correlation = 0.60, N = 302)." (PMID 25200184, 2014). "TRIM68, a ubiquitin E3 ligase that acts as a co-activator of the AR and is up-regulated in prostate cancer, was confirmed as a target for miR-29a and miR-1256." (PMID 25322458, 2014). "An increase of 85 kDa truncated AR fragment with removal of ligand-binding domain in CWR22Rv1 cells, has been suggested to be a mechanism for androgen independence of prostate cancer cells." (PMID 24297527, 2014). "Previous data has alluded to the importance of Hsp90 in AR transcriptional activity in vitro and Hsp90 regulation of AR transactivation in progression to castrate resistant prostate cancer following castration in vivo." (PMID 25072314, 2014). "Endocrine therapies which aimed at inhibiting the androgen receptor (AR) function was the mainstay of treatment for advanced prostate cancer based on that the androgen signaling will promote the proliferation of prostate cancer cell." (PMID 24741584, 2014). "Tests of HHDPCs and various cancer cell lines further showed that HHDPCs expressed the same subtype of potassium channel as that found in the prostate cancer cell line PC-3, which lacks an endogenous AR." (PMID 24742982, 2014). "Of the prostate cancer cells tested, AR positive cell lines were most sensitive to the inhibitory effects of metformin supporting the conclusion that metformin mediates this action at least in part via reduction of AR protein levels." (PMID 24484909, 2014). "In prostate cancer, AR signaling is crucial for development and progression by regulating cell proliferation, differentiation and apoptosis." (PMID 25153862, 2014). "Given the fact that one of the mechanisms that control the expression of the AR in prostate cancer is linked with kinase signaling pathways, we evaluated if the activation of membrane RTKs or their downstream pathways could be associated with the expression of the AR." (PMID 24779793, 2014). "Although androgen independence of prostate cancer growth is a known contributing factor to endocrine resistance, the mechanism of androgen receptor deregulation in endocrine resistance is still poorly understood." (PMID 25296973, 2014). "Given the central importance of AR biology in prostate cancer therapeutics, our focus was on utilizing these techniques to study AR within CTCs." (PMID 25424879, 2014).
prostate carcinoma (continued). "Of note, among the genes repressed by AMPK was KLK2, a prostate cancer marker and a well-established AR target gene that belongs to the same gene family (kallikrein-related peptidases) as prostate specific antigen (PSA / KLK3)." (PMID 25003216, 2014). "In other words, AR and its signaling axis are the most important targets for therapies against advanced prostate cancer." (PMID 24573652, 2014). "Growth and maintenance of normal prostate epithelium and primary prostate cancer tumors is fueled by androgen activation of the AR present in prostate cells." (PMID 24722453, 2014). "PI3K/AKT inhibitors have off-target effects on AR gene expression in prostate cancer cells, which shall be considered when applying these inhibitors to PCa patients, particularly patients under ADT treatment." (PMID 25360799, 2014). "Most of these appear to be involved in the development and/or progression of prostate cancer, and most interact with AR signaling." (PMID 25277175, 2014). "Androgen receptor (AR) is a male hormone receptor, which plays a crucial role in the initiation and growth of prostate cancer." (PMID 24173286, 2014). "Previous studies have showed that AR is involved in the metastasis and invasiveness of prostate cancer cells." (PMID 24397471, 2014). "Strikingly, we identified the AR as one of the most significantly enriched transcription factors mediating gene expression changes downstream of AMPK signalling in prostate cancer cells." (PMID 25003216, 2014). "Specifically in prostate cancer, the regulation of miRNAs by the androgen receptor signalling pathway and their influence on this pathway is also of interest." (PMID 25496077, 2014). "The newly synthesized compounds showed potent androgen receptor antagonists and anti-prostate cancer activities with low toxicity (lethal dose 50 (LD50)) comparable to Bicalutamide as reference drug." (PMID 25421248, 2014). "For example, CDK9, which regulates the androgen receptor through direct phosphorylation and downregulation, decreases AR-transcription and proliferation genes in prostate cancer." (PMID 24576043, 2014). "Conversely, several AR-pathway genes are down-regulated upon progression from a low-grade to high-grade prostate cancer or in the development of metastases." (PMID 25386409, 2014). "In prostate cancer cells, AR-driven up-regulation of CAMKK2 has been shown to result in increased AMPK activity upon androgen stimulation." (PMID 25003216, 2014). "SRC-3, a coactivator of AR that is often upregulated in prostate cancer, is another SPOP ubiquitination target." (PMID 24508459, 2014). "Tissue-based studies of human prostate cancer have shown that stromal AR expression and transcriptional activity downstream of the AR are lower in stromal cells which are derived from carcinomas." (PMID 24949437, 2014). "We have previously reported that AhR is required to maintain hormone independent signaling and growth by the androgen receptor in C4-2 prostate cancer cells." (PMID 24755659, 2014). "FOXA1 has been recognized as an important transcription factor that modulates the functions of steroid receptors such as estrogen receptor in breast cancer and AR in prostate cancer." (PMID 24849812, 2014). "The expression of prostate specific antigen (PSA) has been used extensively as a marker of prostate cancer growth and is a well-known target gene of AR." (PMID 24573652, 2014). "The importance of AR reactivation during castration-resistant progression of prostate cancer has been clinically confirmed by the effective treatment of CRPC by second-generation androgen-AR axis inhibitors including abiraterone and enzalutamide (MDV3100)." (PMID 24508459, 2014). "Inhibition of Hsp27 phosphorylation shifted the association of AR with Hsp90 to the E3 ubiquitin ligase MDM2, increased AR degradation, decreased AR transcriptional activity and increased prostate cancer cell apoptotic rates." (PMID 25339975, 2014).
prostate carcinoma (continued). "Expression of Glycogen Synthase Kinase-3 (GSK-3) is elevated in prostate cancer and its inhibition reduces prostate cancer cell proliferation, in part by reducing androgen receptor (AR) signaling." (PMID 25327559, 2014). "The AR is a ligand-dependent transcription factor that is critical for the development of the human male phenotype and a major player in prostate cancer." (PMID 24398858, 2014). "Overexpression of SPOP in LNCaP prostate cancer cells resulted in a marked reduction of the endogenous level of AR protein in a dose-dependent manner." (PMID 24508459, 2014). "This study demonstrates the relevance of HES6 in the development of androgen resistance and brings forward our understanding of how other factors co-operate with the master regulator of prostate cancer, the AR, to maintain essential pathways for cell survival." (PMID 24737870, 2014). "SENP1 has been shown to be crucial in the development of prostate cancer by modulating the SUMOylation of the androgen receptor." (PMID 24926368, 2014). "In acute myelocytic leukemia, esophageal squamous cell carcinomas, lung adenocarcinomas, thyroid carcinoma, prostate cancer, and AR-positive molecular apocrine breast cancer, FOXA1 acts as an oncogene." (PMID 24512546, 2014). "Androgen receptor (AR) plays a critical role during the development and progression of prostate cancer in which microRNA miR-375 is overexpressed and correlated with tumor progression." (PMID 24173286, 2014). "Herein, we provide evidence that CHOP/GADD153 and BiP activation is essential for degradation of the androgen receptor in prostate cancer." (PMID 24598693, 2014). "Androgen receptor (AR) plays important role in the development, progression, and metastasis of prostate cancer." (PMID 25271736, 2014). "The androgen receptor (AR), a key driver of prostate cancer, regulates prostate cancer cell metabolism by driving the expression of a network of metabolic genes and activates AMPK through increasing the expression of one of its upstream kinases." (PMID 25003216, 2014). "Further studies in prostate cancer cells show androgen receptor (AR) regulates HER3 levels by promoting its degradation by regulating Nrdp1 transcription." (PMID 25400118, 2014). "Activity and abundance of AR protein are crucial for prostate cancer cell proliferation, tumor progression, and development of resistance to antiandrogen therapies." (PMID 24508459, 2014). "Tumors with CAM2KN1 knockdown have reduced expression of p21, Bax and increased AR, pAKTser473, PSA, Bcl-2 and Ki67 expression, suggesting that reduction of CAM2KN1 promotes growth in AR positive prostate cancer cells." (PMID 25296973, 2014). "In contrast, HSP90AA1 is responsible for the degradation of androgen receptor and cell killing following radiation exposure in a prostate cancer cell line." (PMID 25313363, 2014). "In the present study, we provide evidence that all of the known prostate-cancer-associated mutants of SPOP lose their ability to bind to and promote AR ubiquitination and proteasome degradation." (PMID 24508459, 2014). "NPM1 was described to potentiate the action of the androgen receptor (AR) in prostate cancer cells following a direct interaction with this transcription factor on chromatin." (PMID 24796332, 2014). "Though most men with prostate cancer initially respond to these AR-targeted therapies, resistance is inevitable." (PMID 25424879, 2014). "To further strengthen our results obtained from AR-expressing prostate cancer cell lines, we performed high-density cultivation experiments with the AR-negative prostate cancer cell lines PC3 and DU-145." (PMID 24884804, 2014). "A classic example of such acquired resistance is genomic amplification of the androgen receptor (AR) in prostate cancer following treatment with AR antagonists such as bicalutamide." (PMID 25928204, 2014).
prostate carcinoma (continued). "The synthesized compounds were evaluated for their androgen receptor antagonists and anti-prostate cancer activities compared to that of Bicalutamide as a positive control." (PMID 25421248, 2014). "Both acetylation and ubiquitination marks of H2A.Z have been potentially shown to play an important role in transcriptional regulation by the AR and deregulation of histone acetylation and histone H2A.Z composition has been shown in prostate cancer." (PMID 24398858, 2014). "The initial step in determining feasibility of androgen receptor (AR) characterization in CTCs involved spike-in experiments in which cells from the well-established prostate cancer cell line LAPC-4 were introduced into whole blood from healthy donors." (PMID 25424879, 2014). "AR signaling was shown to activate CXCR4 protein expression through KLF5 in prostate cancer cells, propelling chemotactic migration in response to CXCL12, a chemokine abundantly present in the microenvironment and specific sites of metastasis." (PMID 24429391, 2014). "Signaling cross-talk as a mechanism of castrate-resistance in prostate cancer that alters steroid hormone receptor activity and transcriptional regulation of gene expression has been demonstrated for AR in as well as other steroid hormone receptors such as GR." (PMID 25278011, 2014). "The concept of androgen deprivation for the treatment of advanced prostate cancer was developed by Huggins and Hodges in 1941, and up until today, AR—target therapy remains the first line treatment for this disease." (PMID 25309903, 2014). "Specificity of the ISET/IHC technique for the AR in CTC was investigated employing, as controls, human prostate cancer cell lines of known AR status, together with treatment of cells with AZD3514 in order to modulate the levels of the protein." (PMID 24674711, 2014). "For instance, overexpression of HER2 in cell lines of prostate cancer results in increase AR activity and stability." (PMID 24779793, 2014). "In this study, we sought to determine tumor-specific characteristics that influence response of prostate cancers to inhibition of pre-receptor AR signaling, using androgen deprivation combined with the dual SRD5A inhibitor dutasteride." (PMID 25356728, 2014). "The ability of a small molecule inhibitor to prevent nuclear translocation of the AR or to specifically degrade AR protein would be desirable qualities for a drug candidate for the treatment of prostate cancer." (PMID 25268119, 2014). "The human androgen receptor (AR) is a nuclear transcription factor that serves as a major therapeutic target for prostate cancer." (PMID 24573652, 2014). "Androgen deprivation therapy, which disrupts androgen receptor (AR) signaling through androgen ablation or AR antagonists, is the first-line treatment for disseminated prostate cancer." (PMID 24722067, 2014). "The androgen receptor (AR) axis is a major effector in the development and progression of prostate cancer and an important target in the rational drug design of new anticancer agents." (PMID 24674711, 2014). "In this particular study, a rosemary extract standardized to carnosic acid was evaluated for its potential in disrupting the endoplasmic reticulum machinery to decrease the viability of prostate cancer cells and promote degradation of the androgen receptor." (PMID 24598693, 2014). "The androgen receptor (AR) plays a central role in establishing an oncogenic cascade that drives prostate cancer progression." (PMID 25415230, 2014). "The clinical responses to new potent AR antagonists and novel steroid synthesis inhibitors, coupled with evidence of intracrine androgen biosynthesis in prostate cancer suggest that concepts of maximal androgen blockade should be revisited and refined." (PMID 25356728, 2014). "Especially within prostate cancer it is evident that the androgen receptor which acts as a transcription factor for over 800 genes is a critical component of this process." (PMID 24598693, 2014).